NDC1 (NDC1 transmembrane nucleoporin)
Description:
Component of the nuclear pore complex (NPC), which plays a key role in de novo assembly and insertion of NPC in the nuclear envelope. Required for NPC and nuclear envelope assembly, possibly by forming a link between the nuclear envelope membrane and soluble nucleoporins, thereby anchoring the NPC in the membrane.
Synonyms: TMEM48; FLJ10407; NET3; NEDAPA
Tractability: Antibody: its Gene Ontology location is reachable by antibodies, with high confidence; UniProt predicts a signal peptide or a membrane-spanning region. PROTAC: ubiquitination databases record sites on it; its protein half-life has been measured.
Gene: Protein-coding gene on chromosome 1 (53,765,460 to 53,838,560, reverse strand). Ensembl gene ENSG00000058804.
Subcellular location: Nucleus, nuclear pore complex; Nucleus membrane
Subcellular location (Human Protein Atlas): Nuclear membrane; Actin filaments; Plasma membrane
Pathways (Reactome):
Disease: Defective TPR may confer susceptibility towards thyroid papillary carcinoma (TPC); HCMV Early Events; HCMV Late Events; NEP/NS2 Interacts with the Cellular Export Machinery; NS1 Mediated Effects on Host Pathways; Nuclear import of Rev protein; Rev-mediated nuclear export of HIV RNA; SARS-CoV-2 activates/modulates innate and adaptive immune responses; Transport of Ribonucleoproteins into the Host Nucleus; Viral Messenger RNA Synthesis; Vpr-mediated nuclear import of PICs
Metabolism of RNA: Transport of Mature mRNA Derived from an Intronless Transcript; Transport of Mature mRNA derived from an Intron-Containing Transcript; Transport of the SLBP Dependant Mature mRNA; Transport of the SLBP independent Mature mRNA; snRNP Assembly; tRNA processing in the nucleus
Metabolism of proteins: SUMOylation of DNA damage response and repair proteins; SUMOylation of DNA replication proteins; SUMOylation of RNA binding proteins; SUMOylation of SUMOylation proteins; SUMOylation of chromatin organization proteins; SUMOylation of ubiquitinylation proteins
Metabolism: IP3 and IP4 transport between cytosol and nucleus; IP6 and IP7 transport between cytosol and nucleus; IPs transport between nucleus and cytosol; Regulation of Glucokinase by Glucokinase Regulatory Protein
Cell Cycle: Nuclear Pore Complex (NPC) Disassembly; Postmitotic nuclear pore complex (NPC) reformation
Cellular responses to stimuli: Regulation of HSF1-mediated heat shock response
Immune System: ISG15 antiviral mechanism
Gene Ontology:
Molecular function: protein binding; structural constituent of nuclear pore; protein-macromolecule adaptor activity
Biological process: nuclear pore complex assembly; nuclear pore localization; nuclear pore organization; nucleocytoplasmic transport; protein transport
Cellular component: membrane; nuclear envelope; nuclear membrane; nuclear pore; nuclear pore transmembrane ring; cytoplasm
Genetic constraint (gnomAD): Loss-of-function variants: 9 observed, 41.92 expected, observed/expected ratio (o/e) 0.21, 90% interval 0.13 to 0.38. The upper end of that interval is the gene's LOEUF score, 0.38, which puts it in group 1 of 6, group 1 being the genes least tolerant of losing a copy. Missense variants: 435 observed, 487.44 expected, observed/expected ratio (o/e) 0.89, 90% interval 0.82 to 0.97. Synonymous variants: 179 observed, 176.31 expected, observed/expected ratio (o/e) 1.02, 90% interval 0.9 to 1.15.
Homologues: Orthologues: chimpanzee NDC1 (99% identical), macaque NDC1 (98% identical), pig NDC1 (91% identical), dog NDC1 (90% identical), mouse Ndc1 (87% identical), rat Ndc1 (87% identical), rabbit NDC1 (86% identical), guinea pig NDC1 (84% identical), tropical clawed frog ndc1 (57% identical), zebrafish ndc1 (52% identical), Caenorhabditis elegans npp-22 (20% identical), Drosophila melanogaster Ndc1 (19% identical).
Diseases named in the same sentence as NDC1 in open-access papers:
NDC1 is named in the same sentence as 39 diseases in open-access papers, as found by Europe PMC text mining. Sharing a sentence is not in itself a finding about the gene and the disease. The quoted sentences say what the papers report.
lung carcinoma (8 papers, 2018 to 2024). "At present, studies on NDC1 mainly are involved in lung cancer, colon cancer, cervical cancer, esophageal cancer and hepatocellular carcinoma, and there was no previous report in pancreatic cancers." (PMID 37733696, 2023). "Next, we investigated whether NDC1 exerted its function in lung cancer." (PMID 39720592, 2024).
cervical cancer (5 papers, 2021 to 2026). A primary or metastatic malignant neoplasm involving the cervix. "A study examining the signal transduction pathway influenced by NDC1 in cervical cancer (CC) reported that NDC1-mediated cell proliferation and metastasis is modulated partly by activating the Wnt/β-catenin pathway." (PMID 34970494, 2021). "Nuclear division cycle 1 homolog (NDC1 or TMEM48), a transmembrane nucleoporin that resides at the nuclear pore complex (NPC) and the inner nuclear envelope, is markedly upregulated in hepatocellular carcinoma, NSCLC, cervical cancer, and pancreatic cancers." (PMID 41596760, 2026).
pancreatic cancers (3 papers, 2019 to 2026). "The effect of NDC1 on pancreatic cancer cell function was determined by loss-of-function experiments expressed in pancreatic cancer (PC) and contributes to drug resistance and poor prognosis." (PMID 37733696, 2023). "In this study, the expression level of NDC1 in 33 tumors was evaluated by pan-cancer analysis, and the effects of NDC1 on the proliferation, invasion and migration of pancreatic cancer were experimentally verified for the first time." (PMID 37733696, 2023). "To conclude, we identified the importance of NDC1, particularly in pancreatic cancer, by pan-cancer analysis." (PMID 37733696, 2023). "In vitro, we silenced the expression of NDC1 in human pancreatic cancer cell lines BxPC-3 and MIA PaCa-2, respectively, and the interference efficiency was verified by RT-qPCR and Western blot analysis." (PMID 37733696, 2023). "The study reveals that NDC1 could be used as a potential immunological, prognostic and therapeutic target for pancreatic cancer." (PMID 37733696, 2023). "In this study, it is proposed for the first time that NDC1 is related to tumor chemotherapy resistance, and then we need to analyze the specific drugs targeting NDC1 drug sensitivity to pancreatic cancer through in-depth study, in order to further guide clinical drug use." (PMID 37733696, 2023). "The results of Our pan-cancer analysis showed that NDC1 is highly MTT and 5-ethynyl-20 deoxyuridine (EdU) experiments showed that silencing NDC1 could significantly inhibit the proliferation of pancreatic cancer cells." (PMID 37733696, 2023). "This study proved that NDC1 could be used as a potential immunological, prognostic and therapeutic target for pancreatic cancer." (PMID 37733696, 2023). "Furthermore, NDC1 is abnormally expressed in pancreatic cancer, and is closely related to the prognosis of pancreatic cancer patients and chemosensitivity." (PMID 37733696, 2023). "Finally, we conducted in vitro experiments including MTT, scratch, EdU, and apoptosis assays to explore the function of NDC1 in pancreatic cancer cells." (PMID 37733696, 2023). "Notably, we focus on pancreatic cancers to analyze the prognostic significance of NDC1." (PMID 37733696, 2023). "Moreover, the mechanism of NDC1 in pancreatic cancer were further analyzed by GSEA, GSVA." (PMID 37733696, 2023). "However, pan-cancer analysis of NDC1 to fully explore its role in tumors has not been performed and little is reported on its role in pancreatic cancers." (PMID 37733696, 2023).
esophageal squamous cell carcinoma (2 papers, 2021 to 2024). Esophageal squamous cell carcinoma (ESCC) is a type of esophageal carcinoma (EC) that can affect any part of the esophagus, but is usually located in the upper or middle third. "NDC1 has been reported to play a regulatory role in esophageal squamous cell carcinoma (ESCC) and cervical cancer (CC)." (PMID 39720592, 2024). "In a gene enrichment and meta-analytic study, NDC1 was reported as one of the critical genes in addition to NUP107 and NUP155 genes regulating esophageal squamous cell carcinoma (ESCC)." (PMID 34970494, 2021).
Intellectual disability (2 papers, 2024 to 2025). "In our series, individuals with homozygous NDC1 variants present with variable alacrima, achalasia, mild developmental delay/intellectual disability, and peripheral (motor) polyneuropathy, but without endocrine anomalies." (PMID 39003500, 2024).
mesothelioma (2 papers, 2023). A usually malignant and aggressive neoplasm of the mesothelium which is often associated with exposure to asbestos. "In the meantime, NDC1 expression was closely related to the PFS of patients with ACC, COAD, KICH, KIRP, LGG, LIHC, LUAD, Mesothelioma (MESO), PAAD, PRAD, SARC, STAD, UCEC, UVM, and high expression of NDC1 was prognostic for poor PFS of KIRP, LGG, LIHC, PAAD, PRAD and UCEC." (PMID 37733696, 2023). "With this system, we confirmed that knockdown at the TSS of NDC1 and AAAS, two components of the nuclear pore complex, or silencing a putative enhancer of the nuclear receptor NR2F2, decreased the proliferation of mesothelioma cell lines but not of uveal melanoma." (PMID 37400441, 2023).
Achalasia (1 paper, 2024). A disorder of esophageal motility characterized by the inability of the lower esophageal sphincter to relax during swallowing and by inadequate or lacking peristalsis in the lower half of the body of the esophagus. "Our observation shows that NDC1 variants should be considered in individuals with alacrima, achalasia, and neurological defects, mostly severe peripheral neuropathy." (PMID 39003500, 2024). "The majority of the examined individuals with NDC1 variants presented with alacrima and symptoms of achalasia or dysphagia, recurrent vomiting or inability to swallow hard texture food." (PMID 39003500, 2024). "The overlap in phenotypes caused by NDC1 and AAAS variants suggests that impaired recruitment of ALADIN to the NPC contributes to the clinical features shared among the two groups of affected individuals, e.g., alacrima, achalasia, and neurological defects." (PMID 39003500, 2024).
Adrenal insufficiency (1 paper, 2024). Insufficient production of steroid hormones (primarily cortisol) by the adrenal glands. "Taken together, our results implicate biallelic NDC1 variants in the pathogenesis of polyneuropathy and a triple A-like disorder without adrenal insufficiency, by interfering with physiological NDC1 functions, including the recruitment of ALADIN to the NPC." (PMID 39003500, 2024).
diabetics (1 paper, 2023). "In particular, beta cells of diabetics exhibited decreased expression of genes encoding molecular chaperones belonging to the heat shock families Hsp70 (HSPA1B, HSPA7, and HSPA8) and Hsp90 (HSP90AA1 and HSP90AB1) as well as co-chaperones (BAG3 and ST13) and nucleoporins (NDC1, NUP160, and POM121C)." (PMID 37569434, 2023). "We also found changes in the expression of nucleoporin genes such as NDC1, NUP35, NUP58, NUP107, NUP160, and POM121C in pancreatic beta cells of patients with type 2 diabetes mellitus." (PMID 37569434, 2023).
dilated cardiomyopathy (1 paper, 2023). Cardiomyopathy which is characterized by dilation and contractile dysfunction of the left and right ventricles. "Altered expression of NDC1 is observed in ischemic and dilated cardiomyopathy as well as in numerous malignancies." (PMID 37569434, 2023).
heart failure (1 paper, 2025). Inability of the heart to pump blood at an adequate rate to meet tissue metabolic requirements. "In this study, we observed that NDC1 is significantly downregulated under heart failure conditions." (PMID 41477636, 2025). "However, the specific mechanism by which NDC1 acts in heart failure still needs to be clarified through further functional experiments." (PMID 41477636, 2025). "Based on this, we hypothesize that the decreased expression of NDC1 may interfere with the normal function of the nuclear pore complex, disrupting nucleocytoplasmic transport within cardiomyocytes, thereby participating in the pathological progression of heart failure." (PMID 41477636, 2025).
myeloma (1 paper, 2021). "The CERES score of four genes (ISG20, NDC1, SF3B3, UMPS) was significantly lower in the myeloma cell lines (n = 20) compared to in the other cancer cell lines (n = 769)." (PMID 34683129, 2021).
triple-A syndrome (1 paper, 2024). Triple A syndrome is a very rare multisystem disease characterized by adrenal insufficiency with isolated glucocorticoid deficiency, achalasia, alacrima, autonomic dysfunction and neurodegeneration. "Like in triple A syndrome, the neurological defects observed in NDC1 cases affect the central, peripheral, and autonomic nervous system." (PMID 39003500, 2024). "All NDC1 individuals had neurological features from early childhood, while the neurological symptoms in AAAS-related triple A syndrome usually occur at the end of the first, or the beginning of the second decade of life." (PMID 39003500, 2024).
tumor (12 papers, 2016 to 2026). "In contrast, in colorectal cancer, high NDC1 expression is associated with reduced tumor aggressiveness and favorable prognosis, highlighting a context-dependent role." (PMID 41596760, 2026). "It is noting that NDC1 expression was profoundly associated with almost all immune-related genes and common tumor-regulatory genes." (PMID 37733696, 2023). "It was found that high NDC1 expression was highly associated with the development of resistance to multiple anti-tumor drugs." (PMID 37733696, 2023). "Additionally, NDC1 was also demonstrated to be associated with the common tumor-regulatory genes involved in TGF BETA SIGNALING, TNFA SIGNALING, hypoxia, pyroptosis, DNA repair, autophagy and ferroptosis." (PMID 37733696, 2023). "In addition, the expression of NDC1 was associated with the tumor stage in ACC, BRCA, COAD and LIHC." (PMID 37733696, 2023). "In addition, a significant association between the NDC1 expression and immune cell infiltration in tumor microenvironment, immune-related genes, common tumor-regulatory and drug sensitivity was observed." (PMID 37733696, 2023). "Studies have also reported that NDC1 is involved in tumor cell proliferation, migration and invasion." (PMID 37733696, 2023). "Based on the drug sensitivity data of the GDSC database, our study used the R package “pRRophetic” to predict the chemosensitivity of each tumor sample, and further explores the sensitivity of NDC1 to common chemotherapeutic drugs in PAAD." (PMID 37733696, 2023). "The results revealed that NDC1 is closely related to the immunity in tumor and has the potential as a target for tumor therapy." (PMID 37733696, 2023). "Here, the CellMiner database was visited to analyze the relationship between NDC1 expression and some common anti-tumor drugs." (PMID 37733696, 2023). "In the meantime, we also explored the potential association of NDC1 with TME, drug sensitivity, Gene Set Enrichment Analysis (GSEA), Gene Set Variation Analysis (GSVA), tumor mutational burden (TMB), microsatellite instability (MSI)." (PMID 37733696, 2023). "To accurately evaluate the influence of AHCYL1 gene in the tumor microenvironments, we screened out three AHCYL1-associated genes (GNAI3, DDAH1, and NDC1) and established a risk score model." (PMID 35578598, 2022). "The expression of NDC1 is generally associated with the high expression of T cells follicular helper, Neutrophils, T cells CD4 memory activated and the low expression of T cells CD8, NK cells activated and Monocytes in 33 tumor types." (PMID 37733696, 2023). "Combining the correlation between NDC1 expression and some common tumor-regulatory genes and the enriched pathways identified by GSEA and GSVA, we speculated that NDC1 might be implicated in tumor via other pathways, except immune-related pathways, which requires further exploration." (PMID 37733696, 2023). "Functionally, NDC1 facilitates NPC assembly to promote nuclear envelope formation and nuclear growth, and it modulates immune cell infiltration in tumor microenvironment." (PMID 41596760, 2026). "Correlation between NDC1 expression and IC50 of multiple anti-tumor drugs." (PMID 37733696, 2023).
cancer (8 papers, 2018 to 2026). A tumor composed of atypical neoplastic, often pleomorphic cells that invade other tissues. "Univariate Cox regression analysis revealed that NDC1 expression was closely associated with the survival outcome of 15 cancer types, and further Kaplan-Meier survival analysis showed negative associations with the progression-free survival in 14 cancers." (PMID 37733696, 2023). "Specifically, NDC1 was significantly associated with T cells follicular helper in 11 cancer types, with Macrophages M1 in 16 cancer types and with T cells CD4 memory resting in 12 cancer types." (PMID 37733696, 2023). "Correlation analysis was performed to analyze the associations of NDC1 expression in pan-cancer with multiple immune-related genes, including major histocompatibility complexes (MHC), immunostimulator, immunoinhibitor, chemokine and chemokine receptor, immune checkpoint." (PMID 37733696, 2023). "After inhibition of NDC1, the protein expression of NDC1 in cancer cells was remarkably reduced, and the protein expression of NUP155 remained unchanged." (PMID 39720592, 2024). "In the current study, three databases, TCGA, Genotype-Tissue Expression (GTEx) and Cancer Cell Line Encyclopedia (CCLE), were visited to study the expression of NDC1 in 33 types of cancer and explore its prognostic significance." (PMID 37733696, 2023). "Altered NDC1 expression has been found in a variety of cancers." (PMID 39720592, 2024). "High expression of NDC1 was demonstrated in 28 cancer types." (PMID 37733696, 2023). "In the present study, a pan-cancer analysis of NDC1 was performed using a bioinformatic approach." (PMID 37733696, 2023). "Expression of NDC1 was analyzed in 33 cancer types based on data from TCGA and GTEx." (PMID 37733696, 2023). "The prognostic significance of NDC1 for overall survival (OS) and progression-free survival (PFS) of cancer patients was analyzed by Univariate Cox regression." (PMID 37733696, 2023).
heart (1 paper, 2012). "This study shows alterations in specific proteins (NDC1, Nup160, Nup153 and Nup93) that compose NPC in ischaemic and dilated human heart." (PMID 23152829, 2012).
NDC1 also shares sentences with these, for which no sentence is quoted: hepatocellular carcinoma (3 papers); non-small cell lung carcinoma (3); breast carcinoma (2); colon cancer (2); melanoma (2); uveal melanoma (2); developmental delay (1); endocrine disorders (1); esophageal cancer (1); gastric cancer (1); head and neck squamous cell carcinoma (1); Immunodeficiency (1); liver cancer (1); lymphoma (1); myeloproliferative neoplasm (1); neuropathy (1); Obesity (1); ovarian carcinoma (1); peripheral neuropathy (1); polyneuropathy (1); renal cell carcinoma (1); testicular embryonal carcinoma (1); type 2 diabetes mellitus (1).